SLC7A7 (solute carrier family 7 member 7)
Diseases named in the same sentence as SLC7A7 in open-access papers (continued):
Sharing a sentence is not in itself a finding about the gene and the disease.
tumor (13 papers, 2016 to 2025). "LAT1, a protein encoded by SLC7A5 and a member of the same family as SLC7A7, is critical for tumor angiogenesis by regulating cell proliferation, translation, and pro-angiogenic VEGF-A signaling." (PMID 40075158, 2025). "However, in a study of NSCLC, SLC7A7 was indicated to be involved in the infiltration of neutrophils, tumor-associated macrophages (TAMs), and DCs in a variety of cancers, as well as in the regulation of T-cell exhaustion and Tregs in NSCLC12." (PMID 39730571, 2024). "However, the underlying functions and mechanisms of SLC7A7 in tumor progression and tumor immunology are still unclear." (PMID 33632211, 2021). "Compared to the vehicle control, SLC7A7 knockdown significantly delayed tumor volume and weight and increased the expression of miR-152-3p, which consequently resulted in a decrease in CD32 and FGFR3 levels." (PMID 40075158, 2025). "Immunohistochemical staining revealed a significant decrease in CD31 expression in the SLC7A7 knockdown group, suggesting a reduction in tumor angiogenesis following SLC7A7 knockdown." (PMID 40075158, 2025). "Studies have shown that overexpression of SLC7A7 can decrease the proportion of apoptotic Jurkat cells, increase the proportion of G1 phase cells, and enhance the migration and invasion of tumor cells." (PMID 40075158, 2025). "Collectively, these findings strongly indicate that the silencing of SLC7A7 exerts inhibitory effects on angiogenesis, thereby impeding tumor progression in vivo." (PMID 40075158, 2025). "Using a chick chorioallantoic membrane (CAM) model, we validated that the conditioned medium (CM) from SLC7A7-knockdown tumor cells led to a significant reduction in the number and the bifurcation of vessels within the CAM." (PMID 40075158, 2025). "Elevated SLC7A7 levels in tumor cells can lead to decreased intracellular arginine, promoting cell migration and invasion while inhibiting apoptosis." (PMID 40075158, 2025). "The upregulation of SLC7A7 increased the levels of arginine in tumor cells, thus promoting their migration and invasion." (PMID 38244585, 2024). "Our results indicate that SLC7A7 has the potential to promote tumor progression and serve as a potential therapeutic target for CRC." (PMID 39730571, 2024). "In CRC patients, upregulation of SLC7A7 in tumor tissues was significantly related to lower survival." (PMID 39730571, 2024). "Afterward, functional experiments were conducted in vitro to investigate how SLC7A7 affects tumor metastasis." (PMID 39730571, 2024). "Tumor tissues with higher SLC7A7 expression levels were accompanied by lower Neutrophil cells, NKT cells, and Th17 cells." (PMID 39730571, 2024). "SLC7A7 expression was analyzed using the Oncomine database and Tumor Immune Estimation Resource (TIMER) site." (PMID 33632211, 2021). "One the other hand, overexpression of SLC7A7 in tumor cells in turn leads to elevated arginine in the microenvironment." (PMID 33632211, 2021). "More attention should therefore be focused on SLC7A7 as a key factor mediating DC infiltration and tumor metastasis." (PMID 33632211, 2021). "In addition, both RNA and protein levels of SLC7A7 were significantly elevated in BCa samples, and further elevated in MIBCa tumor tissues." (PMID 40075158, 2025). "To investigate this hypothesis, we harvested the supernatants from tumor cells with silenced SLC7A7." (PMID 40075158, 2025). "To investigate whether SLC7A7 is involved in this effect, we detected its expression in tumor tissues." (PMID 39996726, 2025). "To explore the molecular intricacies underlying SLC7A7-mediated angiogenesis, we hypothesized that tumor cells with high SLC7A7 expression may influence the TME, thereby promoting angiogenic processes." (PMID 40075158, 2025).
tumor (continued). "Results showed that ATF3 knockdown reduced SLC7A7 expression, activated mTORC1 signaling, and upregulated lipogenesis-related enzymes, implying that downregulation of SLC7A7 may contribute to the enhanced tumor growth observed upon ATF3 knockdown." (PMID 39996726, 2025). "This negative correlation between methylation and gene expression suggests that SLC7A7 methylation in CRC may influence tumor progression by suppressing its expression." (PMID 39730571, 2024). "Overexpressed SLC7A7 could accelerate the velocity that cancer cells obtained arginine from tumor microenvironment, and then exacerbate the arginine deficiency in tumor microenvironment." (PMID 37214463, 2023). "Hence, our study provides novel insights for understanding the potential role of SLC7A7 in tumor immunology and its use as a cancer biomarker or therapy target." (PMID 33632211, 2021). "One the one hand, the relative deficiency of intracellular arginine due to the elevation of SLC7A7 level in tumor cells could promote cell migration and invasion, and inhibit cell apoptosis." (PMID 33632211, 2021). "In addition, the correlation between SLC7A7 expression and marker genes of immune cells suggested a role for SLC7A7 in regulating tumor immunology in NSCLC." (PMID 33632211, 2021). "Studies about the tumor progression part of SLC7A7 are too limited." (PMID 33384961, 2020). "In addition, bioinformatics analysis revealed that SLC7A7 may promote EMT by activating the Wnt/β-catenin signaling pathway, a pathway known to be closely associated with tumor cell migration and invasion." (PMID 39730571, 2024). "However, the relationships between SLC7A7 and prognosis and tumor-infiltrating lymphocytes in different cancers remain unclear." (PMID 33632211, 2021). "However, the exact relationship between SLC7A7 and tumor angiogenesis remains unclear." (PMID 40075158, 2025). "In contrast, SLC7A7 and SLC24A4 exhibit a more widespread expression in TAMs, while SLC1A6 was detected in only a small fraction of tumour cells." (PMID 38687049, 2024). "Given the lack of a sensitive SLC7A7 antibody for immunohistochemistry, we analyzed tumor lysates via Western blotting." (PMID 39996726, 2025). "We analyzed the expression of SLC7A7 methylation in different human cancer types, tumor tissues, and normal tissues in the TCGA dataset in CRC, SLC7A7 methylation is hyper-expressed within the tumor tissue." (PMID 39730571, 2024). "In contrast, SLC7A7 expression was not significantly correlated with tumor purity or infiltrating levels of CD8 + T cells, CD4 + T cells or neutrophils in UVM." (PMID 33632211, 2021). "Interestingly, similar to the results obtained from bulk analysis, the single‐cell data showed a higher detection of SLC43A3, SLC2A10, SLC25A43, SLC7A7 and SLC47A1, which are highly expressed in tumour tissues, relative to SLC1A6 and SLC24A4, which are lowly expressed." (PMID 38687049, 2024).
cancer (8 papers, 2014 to 2025). A tumor composed of atypical neoplastic, often pleomorphic cells that invade other tissues. "In our analysis of clinical BCa samples, both protein and mRNA levels of SLC7A7 were significantly elevated, with this upregulation closely associated with muscular invasion, suggesting a pro-cancer role in BCa progression." (PMID 40075158, 2025). "In conclusion, we explored the diagnostic prognostic value of SLC7A7 in pan-cancer utilizing multiple bioinformatics analyses." (PMID 39730571, 2024). "To better understand the relevance and underlying mechanisms of SLC7A7 expression in cancer, we investigated the functional state of SLC7A7 across different cancer types in the CancerSEA database." (PMID 33632211, 2021). "This suggests that the role of SLC7A7 methylation in CRC may be different from that in other cancers and may provide new insights into the pathogenic mechanisms specific to CRC." (PMID 39730571, 2024). "Taken together, these results indicate that the expression level of SLC7A7 in cancer is closely related to the infiltration of multiple immune cells." (PMID 39730571, 2024). "Further comparative analyses revealed that although methylation of SLC7A7 occurs in multiple cancer types, its elevation in CRC is specific." (PMID 39730571, 2024). "We investigated the correlations between the mRNA expression levels of SLC7A7 and prognosis in cancer patients using the PrognoScan database." (PMID 33632211, 2021). "To better understand the relevance and underlying mechanisms of SLC7A7 expression in cancer, we investigated the functional states of SLC7A7 across different cancer types." (PMID 33632211, 2021). "In the present study, we examined SLC7A7 expression and prognostic values in various types of cancer using independent datasets in Oncomine and GEO data in PrognoScan." (PMID 33632211, 2021). "To further evaluate SLC7A7 expression in various cancer types, we investigated SLC7A7 expression using the RNA-seq data of multiple malignancies in TCGA." (PMID 33632211, 2021). "First, the expression profiles of SLC7A7 in various cancer types and corresponding normal controls were investigated in the Oncomine database." (PMID 33632211, 2021). "Another important aspect of this study was the correlation between SLC7A7 expression and diverse immune infiltration levels in cancer, especially in NSCLC." (PMID 33632211, 2021). "Herein, variations in SLC7A7 expression levels were found to be correlated with prognosis in different types of cancer." (PMID 33632211, 2021). "We analyzed the mRNA expression levels of SLC7A7 among 31 different human cancer tissues." (PMID 39730571, 2024). "The relationships between SLC7A7 and cancer immune infiltrates was investigated by TIMER." (PMID 33632211, 2021). "SLC7A7 was differentially expressed between cancer and normal tissues in many types of cancer." (PMID 33632211, 2021). "The discrepancies in SLC7A7 expression levels in different cancer types in different databases may be a reflection of data collection methods and the underlying mechanisms pertinent to different biological properties." (PMID 33632211, 2021). "The functional state of SLC7A7 in various types of cancers was analyzed by CancerSEA." (PMID 33632211, 2021). "SLC7A7 is highly expressed in a variety of cancers and could be a predictor of poor prognosis." (PMID 40075158, 2025). "In addition, SLC7A7 plays a crucial role in cancer initiation and progression." (PMID 39730571, 2024). "Hence, these results confirmed that SLC7A7 is of great importance for assessing the prognosis of certain types of cancer, with increased and reduced SLC7A7 expression having different prognostic value depending on the type of cancer." (PMID 33632211, 2021). "In addition, SLC7A7 had a significant impact on the prognosis of diverse cancers." (PMID 33632211, 2021). "The different expression of NLRC5, SLC7A7 and PKN1 provided valuable information for future investigation and development of novel cancer therapy." (PMID 35745070, 2022).
cancer (continued). "However, the expression of SLC7A7 was higher in BRCA, CHOL, ESCA, HNSC and STAD tissues than in corresponding normal tissues, but was lower in KICH, KIRC, KIRP, LIHC, LUAD and LUSC cancers by analysis of TCGA data." (PMID 33632211, 2021).
metabolic disease (8 papers, 2017 to 2025). A congenital disorder (due to inherited enzyme abnormality) or acquired (due to failure of a metabolically important organ) disorder resulting from an abnormal metabolic process. "These additional putative mono/oligogenic SLE genes are involved in type I IFN regulation (DDX58, NLRC4 and PACSIN1), disruption of B cell and T cell tolerance (DOCK8, FAS and LRBA) and metabolic disorders (CYBB, MAN2B1, SLC7A7)." (PMID 40386946, 2025).
kidney disease (1 paper, 2025). "Considering the prevalence of kidney disease among LPI patients, we hypothesized that Slc7a7 deficiency might lead to kidney dysfunction, resulting in diminished erythropoietin levels and impaired RBC maturation." (PMID 39881295, 2025).
SLC7A7 also shares sentences with these, for which no sentence is quoted: Failure to thrive (3 papers); kidney failure (2); acute lymphoblastic leukemia (1); acute myeloid leukemia (1); alpha-mannosidosis (1); amyloidosis (1); autoimmune disease (1); Autoimmunity (1); bladder cancer (1); cholangiocarcinoma (1); chronic kidney disease (1); Coma (1); developmental delay (1); esophageal carcinoma (1); glomerulonephritis (1); head and neck squamous cell carcinoma (1); heart septal defect (1); Hyperornithinemia-hyperammonemia-homocitrullinuria (1); immune deficiencies (1); infection (1); infectious disease (1); keratoconus (1); leukemia (1); lung adenocarcinoma (1); lung squamous cell carcinoma (1); lymphoma (1); lymphoproliferative disorders (1); mitochondrial disease (1); Osteopenia (1); porphyria (1).
A further 8 diseases each share a sentence with SLC7A7 in 1 paper.